ENPP3 (ectonucleotide pyrophosphatase/phosphodiesterase 3)
Description:
Hydrolase that metabolizes extracellular nucleotides, including ATP, GTP, UTP and CTP. Also hydrolyzes extracellular 2',3'-cGAMP (cyclic GMP-AMP), a second messenger that activates TMEM173/STING and triggers type-I interferon production, and is therefore involved in the regulation of innate immune response. 2',3'-cGAMP appears to be further processed to GMP, AMP and inorganic phosphate. Limits mast cells and basophils response during inflammation and during the chronic phases of allergic responses by eliminating extracellular ATP, a signaling molecule activating these cells in an autocrine manner. Metabolizes extracellular ATP in the lumen of the small intestine, and thereby prevents ATP-induced apoptosis of intestinal plasmacytoid dendritic cells (By similarity). Has a broad specificity and can also hydrolyze UDP-GlcNAc into UMP and GlcNAc-1-phosphate and potentially several other intracellular nucleotide sugars, including UDP-GalNAc, CMP-NeuAc, GDP-Fuc, and UDP-GlcA. Thereby, could modulate glycan biosynthesis and protein glycosylation (By similarity). Can hydrolyze extracellular dinucleoside polyphosphates, including the vasoactive adenosine polyphosphates as well. In addition, displays an alkaline phosphodiesterase activity in vitro.
Synonyms: NPP3; PD-Ibeta; CD203c; PDNP3; gp130RB13-6; B10
Tractability: Small molecule: a structure with a bound ligand is known; a high-quality ligand is known. Antibody: UniProt places it where antibodies can reach, with high confidence; its Gene Ontology location is reachable by antibodies, with high confidence; UniProt predicts a signal peptide or a membrane-spanning region. PROTAC: a small molecule that binds it is known. Other modalities: a drug acting on it is in phase 2 or 3 trials.
Target class: Enzyme; Hydrolase
Gene: Protein-coding gene on chromosome 6 (131,628,292 to 131,747,418, forward strand). Ensembl gene ENSG00000154269.
Subcellular location: Cell membrane; Apical cell membrane; Secreted
Pathways (Reactome):
Metabolism: Vitamin B5 (pantothenate) metabolism
Gene Ontology:
Molecular function: ATP diphosphatase activity; bis(5'-adenosyl)-pentaphosphatase activity; bis(5'-adenosyl)-triphosphatase activity; bis(5'-nucleosyl)-tetraphosphatase (asymmetrical) activity; calcium ion binding; cyclic-GMP-AMP hydrolase activity; GTP diphosphatase activity; nucleoside triphosphate diphosphatase activity; phosphodiesterase I activity; UTP diphosphatase activity; zinc ion binding; 5'-nucleotidase activity; hydrolase activity; metal ion binding; nucleic acid binding; pyrophosphatase activity
Biological process: ATP metabolic process; inorganic diphosphate transport; negative regulation of cGAS/STING signaling pathway; nucleoside triphosphate catabolic process; phosphate-containing compound metabolic process; pyrimidine nucleotide metabolic process; basophil activation involved in immune response; negative regulation of inflammatory response; negative regulation of mast cell activation involved in immune response; negative regulation of mast cell proliferation; phosphate ion homeostasis
Cellular component: apical plasma membrane; external side of plasma membrane; extracellular exosome; extracellular region; perinuclear region of cytoplasm; plasma membrane; cell surface
Genetic constraint (gnomAD): Loss-of-function variants: 46 observed, 48.57 expected, observed/expected ratio (o/e) 0.95, 90% interval 0.75 to 1.21. The upper end of that interval is the gene's LOEUF score, 1.21, which puts it in group 5 of 6, group 1 being the genes least tolerant of losing a copy. Missense variants: 462 observed, 493.03 expected, observed/expected ratio (o/e) 0.94, 90% interval 0.87 to 1.01. Synonymous variants: 180 observed, 168.8 expected, observed/expected ratio (o/e) 1.07, 90% interval 0.94 to 1.21.
Homologues: Orthologues: chimpanzee ENPP3 (99% identical), macaque ENPP3 (97% identical), dog ENPP3 (85% identical), pig ENPP3 (83% identical), rabbit ENPP3 (83% identical), mouse Enpp3 (81% identical), rat Enpp3 (79% identical), guinea pig ENPP3 (65% identical), tropical clawed frog enpp3 (62% identical), Caenorhabditis elegans C27A7.3 (22% identical), Caenorhabditis elegans enpp-1 (22% identical), Caenorhabditis elegans C01B10.9 (17% identical). Paralogues in human: ENPP1 (53% identical), ENPP2 (43% identical), ENPP4 (17% identical), ENPP5 (17% identical), ENPP7 (15% identical), ENPP6 (15% identical).
Diseases named in the same sentence as ENPP3 in open-access papers:
ENPP3 is named in the same sentence as 73 diseases in open-access papers, as found by Europe PMC text mining. Sharing a sentence is not in itself a finding about the gene and the disease. The quoted sentences say what the papers report.
renal cell carcinoma (5 papers, 2021 to 2025). "In addition to regulating the tumour immune environment, cell-intrinsic expression of ENPP3 has been reported to promote cell migration and to be essential for the growth of renal cell carcinoma cell lines, further supporting a pro-tumour function." (PMID 40336011, 2025). "Moreover, an antibody-drug conjugate (ADC) targeting ENPP3 is undergoing phase II clinical trials for advanced renal cell carcinoma treatment, offering a promising therapeutic approach for EMs." (PMID 38149831, 2023). "Similarly, ENPP3 promotes cell-intrinsic growth and migration of renal cell carcinoma cells, but also regulates the availability of STING ligands for immune cells, and given its central role in RNA capping, RNGTT has the potential to affect many other genes with indirect effects on tumour growth." (PMID 40336011, 2025). "Another protein from this family, ENPP3, underwent clinical trials for ADC development targeting renal cell carcinoma (RCC)." (PMID 39186767, 2024). "AGS-16C3F, an ADC targeting ectonucleotide pyrophosphatase/phosphodiesterase 3 (ENPP3, CD203a) conjugated to MMAF, is now a subject of phase II clinical trials for the therapy of renal cell carcinoma (RCC)." (PMID 34203870, 2021). "In renal cell carcinoma (RCC), BsAbs target ENPP3 × CD3, HER2 × HER3, and PD-1 × CTLA-4." (PMID 40260236, 2025).
glioma (4 papers, 2012 to 2024). A benign or malignant brain and spinal cord tumor that arises from glial cells (astrocytes, oligodendrocytes, ependymal cells). "(v) Enpp3 expression has also been shown to be involved in the invasive properties of tumor cells of glioma and colon carcinoma, but the mechanism for these effects is unknown." (PMID 39641818, 2024).
diabetes (3 papers, 2013 to 2025). "Both Enpp3 and Enpp1 have both been associated with diabetes." (PMID 23826075, 2013). "(vi) Finally, there is circumstantial evidence that Enpp3 may be also related to diabetes, though a direct link to the insulin receptor, as that known to occur in the case of ENPP1, has not been reported." (PMID 39641818, 2024).
endometriosis (3 papers, 2019 to 2020). The growth of functional endometrial tissue in anatomic sites outside the uterine body. "ENPP3, which is higher abundant during the secretory phase and lower in endometriosis, is known to interact with nucleotides and modifies the glycosylation and, therefore, the activation state of other proteins." (PMID 30669470, 2019).
clear cell renal cell carcinoma (2 papers, 2023). "A phase I trial of an ADC targeted against ENPP3, a protein expressed by most clear cell renal cell carcinomas, has reported tolerable toxicity and efficacy." (PMID 37631232, 2023). "Increased levels of ENPP3 have been observed in conditions, such as clear cell renal cell carcinoma, bile duct carcinoma, and colorectal cancer, positioning ENPP3 as a potential tumor marker." (PMID 38149831, 2023).
hepatocellular carcinoma (2 papers, 2018 to 2025). A malignant tumor that arises from hepatocytes. "In conclusion, this study identified and internally evaluated a five-gene metabolic signature (PLPPR1, CNTN3, HOXA10, HAGLR, and ENPP3) associated with immunotherapy response in hepatocellular carcinoma through integrative analysis of multiple transcriptomic datasets." (PMID 41515582, 2025).
lung fibrosis (2 papers, 2016 to 2023). "According to the results of qRT-PCR, the expression levels of ENPP3, PDE7B, and ENTPD1 were elevated, while the expression levels of PNMT, GPX3, and POLR3H were decreased in the lung tissues of bleomycin-induced pulmonary fibrosis mice compared with the sham group." (PMID 36923791, 2023).
maturity onset diabetes (2 papers, 2022 to 2024). "The results of GSEA suggested that the ENPP3 was enriched in Toll like receptor signaling pathway and natural killer cell mediated cytotoxicity, NUDT12 was enriched in maturity onset diabetes of the young and insulin signaling pathway." (PMID 38464965, 2024). "GSEA suggested that ENPP3 was enriched in Toll like receptor (TLR) pathway, NUDT12 was enriched in maturity onset diabetes of the young and insulin pathway." (PMID 38464965, 2024).
atherosclerosis (1 paper, 2024). A disease characterized by the build-up of fatty material and calcium deposition in the arterial wall resulting in partial or complete occlusion of the arterial lumen. "Thus, reduced expression of ENPP3 and subsequent increase in extracellular ATP concentration may be one of the mechanisms by which high TG induces inflammation and promotes atherosclerosis." (PMID 39276247, 2024).
COVID-19 (1 paper, 2022). A disease caused by infection with severe acute respiratory syndrome coronavirus 2. "Herein, we detected the gene expression of ENPP1, ENPP2, ENPP3, ENTPD1 (CD39), ENTPD5, and NT5E (CD73) in the whole blood of COVID-19 patients." (PMID 36248842, 2022). "There is a significant reduction in the expression of ENPP1, ENPP2, ENPP3, and NT5E in the blood of patients with severe COVID-19 when compared to HDs and a lower expression of ENPP2 and ENPP3 when compared to mild hospitalized cases." (PMID 36248842, 2022).
female infertility (1 paper, 2016). Diminished or absent ability of a female to achieve conception. "It will be important to further explore the molecular mechanism of ENPP3 in endometrial receptivity and implantation, particularly in female infertility." (PMID 27665743, 2016).
neuroblastoma (1 paper, 2016). Neuroblastoma (NB) is the most common solid, extracranial childhood tumor. "Recently it was shown that ENPP3 regulates the glycosyltransferase activity, which facilitates the glycosylation of many proteins by inhibiting an intrinsic factor for N-acetylglucosaminyltransferase GnT-IX (GnT-Vb) in murine neuroblastoma Neuro 2a cells." (PMID 27665743, 2016).
Neurotoxicity Syndromes (1 paper, 2024). "A total of 59 biomarker-associated diseases were obtained through the CTD database, and a total of 55 biomarker-disease association pairs were obtained, such as ENPP3 and Glucose Intolerance, and NUDT12 and Neurotoxicity Syndromes." (PMID 38464965, 2024).
osteoarthritis (1 paper, 2013). A noninflammatory degenerative joint disease occurring chiefly in older persons, characterized by degeneration of the articular cartilage, hypertrophy of bone at the margins and changes in the synovial membrane. "One of these, Enpp3, a pyrophosphatase, has been previously associated with osteoarthritis." (PMID 23382930, 2013).
papillary thyroid carcinoma (1 paper, 2014). "While ENPP3 is involved in tumor cell migration and KCNJ2 is overexpressed in papillary thyroid carcinoma, the role of either of these factors is unknown in RCC." (PMID 24979721, 2014).
peripheral nerve injury (1 paper, 2018). Injury to a peripheral nerve. "Based on our findings, GPNMB, ENPP3, Thbs2, and Lgals3 may play a key role in repair of SCs after peripheral nerve injury." (PMID 30186571, 2018).
psoriasis (1 paper, 2021). An autoimmune condition characterized by red, well-delineated plaques with silvery scales that are usually on the extensor surfaces and scalp. "As a result, we found that the mRNA expression level of KIT, ENPP3, CMA1, CTSG, TPSAB1 and TPSG1 is decreased in PP compared with PN and NN, indicating the fraction of total mast cells is decreased in psoriasis." (PMID 34887864, 2021).
Tinnitus (1 paper, 2024). Tinnitus is an auditory perception that can be described as the experience of sound, in the ear or in the head, in the absence of external acoustic stimulation. "The most downregulated genes in the tinnitus (when compared to the non-tinnitus group) were LOC103690064, AABR07048397.1, Trpv1, AABR07061378.1, Ncaph, Spata20, Rps19, Enpp3, Grtp1, and Glra1." (PMID 38562529, 2024).
viral infection (1 paper, 2025). "More recently, ENPP3 has also been implicated in the regulation of extracellular levels of cGAMP (2′3′-cyclic guanosine monophosphate), a second messenger for the activation of the STING (stimulator of interferon genes) pathway and the production of type I IFNs in viral infection and cancer." (PMID 40336011, 2025).
Zinc deficiency (1 paper, 2018). A deficiency of the essential metal Zinc; an essential cofactor for many enzymes. "For example, both high expression of TNAP, ENPP1, ENPP3, and NT5E/CD73 and low expression of ENTPD1/CD39 increase the susceptibility of cells to the effects of zinc deficiency on extracellular adenine-nucleotide metabolism." (PMID 30271993, 2018). "Zinc deficiency severely impairs the activities of major ectoenzymes (ENPP1, ENPP3, NT5E/CD73, and TNAP), and also strongly suppresses adenine-nucleotide hydrolysis in cell-membrane preparations or rat plasma, thereby increasing ATP and ADP levels and decreasing adenosine levels." (PMID 30271993, 2018). "The quantification of each adenine nucleotide and adenosine hydrolyzed from ATP revealed that the effects of zinc deficiency varied depending on the cell type, which can be attributed to the distinct expression pattern and level of ENTPD1/CD39, ENPP1, ENPP3, NT5E/CD73, TNAP, PAP, and their isozymes." (PMID 30271993, 2018).
tumor (21 papers, 2014 to 2026). "Supporting a pro-tumour role, loss of ENPP3 cGAMP hydrolase activity in mice renders them more resistant to primary tumour growth and metastasis." (PMID 40336011, 2025). "ENPP3 is involved in various physiological and pathological processes, such as nucleotide and phospholipid signaling, bone mineralization, fibrotic diseases and tumor-associated immune cell infiltration." (PMID 38464965, 2024). "ENPP3 overexpression accelerated tumor growth, while its knockdown or antibody blockade inhibited progression and synergized with anti-PD-L1." (PMID 41715305, 2026). "Its inhibition reactivates STING-dependent anti-tumor immunity, providing a strong preclinical rationale for targeting ENPP3 therapeutically." (PMID 41715305, 2026). "Genetic or functional disruption of ENPP3 enhances antitumor immunity in a STING-dependent manner, implicating ENPP3 in immune regulation within the tumor microenvironment." (PMID 41515582, 2025). "ENPP1 is widely expressed throughout the body, while ENPP3 is predominantly expressed in immune cells and tumor tissues." (PMID 40535334, 2025). "Recent studies have shown that ENPP3 is involved in the invasion of tumor cells, which is similar to the process of VSMCs migration and proliferation from the media to the intima and forms restenotic plaques." (PMID 34504438, 2021). "Importantly, we also show that, as with ENPP1, selectively abolishing ENPP3's cGAMP hydrolysis activity results in diminished cancer growth and metastasis of certain tumor types in a stimulator of interferon genes (STING)-dependent manner." (PMID 38749434, 2024). "In turn, the reduction in ENPP3 potential could impede tumour progression." (PMID 40336011, 2025). "AOX1, ENPP3, and NMRK2 were down-modulated in all analyzed tumor specimens, whereas PARP1 was up-regulated." (PMID 38254798, 2024). "Specifically, some genes were significantly modulated in all three tumors in the same way: AOX1, ENPP3, and NMRK2 were down-modulated in tumor specimens, whereas PARP1 was up-regulated." (PMID 38254798, 2024). "ENPP3 expression pattern is distinct from that of ENPP1, and ENPP3 is more active at acidic pH than ENPP1, which might confer an advantage in an acidic tumor microenvironment." (PMID 39728440, 2024).
cancer (7 papers, 2014 to 2025). A tumor composed of atypical neoplastic, often pleomorphic cells that invade other tissues. "In detail, while the ADORA2B-PNP pair is associated to lower survival in uterus, P2RY4 axes with ENPP3 and ENTPD1 are associated to higher survival in the same cancer." (PMID 38723607, 2024). "Moreover, we implicate several of these gene hits not only in ccRCC for the first time (BHLHB3, CAMK1, CDH13, ENPP3, KCNJ2, KSR1, PLOD2, and TCF8), but also in a cancer model for the first time (CEP290, EFCAB3, PGBD5, RAPGEF5, SSPN, and TOX2)." (PMID 24979721, 2014). "Our work demonstrates that ENPP1 and ENPP3 non-redundantly dampen extracellular cGAMP-STING signaling, pointing to ENPP3 as a target for cancer immunotherapy." (PMID 38749434, 2024).
ENPP3 also shares sentences with these, for which no sentence is quoted: Allergy (15 papers); allergic rhinitis (5); anaphylaxis (5); asthma (5); systemic mastocytosis (4); allergic asthma (3); autoimmune disease (2); chronic myelogenous leukemia (2); colon carcinoma (2); colorectal cancer (2); food allergies (2); melanoma (2); peanut allergy (2); renal carcinoma (2); urticaria (2); airway allergy (1); atopic dermatitis (1); bile duct carcinoma (1); cholangiocarcinoma (1); chronic renal failure (1); colitis (1); Diarrhea (1); eczema (1); egg allergy (1); experimental autoimmune encephalomyelitis (1); glial cell tumor (1); heart failure (1); hepatoblastoma (1); inflammation (1); inflammatory bowel disease (1).
A further 21 diseases each share a sentence with ENPP3 in 1 paper.